CCL3 (C-C motif chemokine ligand 3)
Diseases named in the same sentence as CCL3 in open-access papers (continued):
Sharing a sentence is not in itself a finding about the gene and the disease.
rheumatoid arthritis (26 papers, 2012 to 2025). A chronic, systemic autoimmune disorder characterized by inflammation in the synovial membranes and articular surfaces. "CCL3 also plays a role in inflammatory bone loss, in particular in animal models of rheumatoid arthritis (RA)." (PMID 31572390, 2019). "Studies have shown that CCL3 is central in the promotion and migration of inflammatory components to tissues in other autoimmune diseases, particularly rheumatoid arthritis, where it participates in the pathogenesis of cartilage bone destruction." (PMID 39436967, 2025). "CCL2/MCP-1 and CCL3/MIP-1α are substances primarily identified in patients with rheumatoid arthritis." (PMID 34199256, 2021). "Recently, increased miR-155 is shown to be associated with increased production of the chemokines CCL3, CCL4, CCL5 and CCL8, and regulate chemokine receptor expression in rheumatoid arthritis patients." (PMID 29162878, 2017). "Increased expression levels of CCL3 in PMN-O from CP patients could be also linked to the amplification of neutrophil recruitment to the mouth, similar to what was reported in the synovial fluid from patients with rheumatoid arthritis." (PMID 23874838, 2013). "Studies showed that various chemokines participated in RJD pathogenesis: rheumatoid arthritis patients exhibit increased levels of plasma CCL2, CCL3, CCL4, and CXCL10 and psoriatic arthritis patients also exhibited high values of CCL2 and CXCL10." (PMID 38622714, 2024). "T cell CXCR3 and its ligands CXCL9 and CXCL10 as well as CCR5 and its ligands CCL3 and CCL5 are expressed at higher levels in disorders where Th1 immune responses predominate such as multiple sclerosis and rheumatoid arthritis." (PMID 36670847, 2023). "In the bootstrap resampling, we selected several important rheumatoid arthritis genes such as MMP genes (MMP1, MMP3), CCL genes (CCL3, CCL4, and CCL26), and IL genes (IL6, IL8, IL19, and IL24)." (PMID 31371761, 2019). "Interestingly, the five cytokines (CCL2, CCL3, CCL20, CXCL1, and IL8) that are involved in the leukocyte infiltration in the blood vessel of rheumatoid arthritis patients are also found in the xenoAMP(S)-poly(I:C) activated HDMVEC." (PMID 38306481, 2024).
pneumonia (25 papers, 2009 to 2025). An acute, acute and chronic, or chronic inflammation focally or diffusely affecting the lung parenchyma, caused by an infection in one or both of the lungs (by bacteria, viruses, fungi, or mycoplasma.). "Coinfection led to prolonged viral persistence, enhanced pulmonary immune cell infiltration, and significantly elevated levels of inflammatory cytokines (IL-6, CCL3, CCL4, and G-CSF; p < 0.05–0.001), culminating in severe pneumonia." (PMID 41226526, 2025). "Increased transcription of chemokine receptors CCR2 (CCL2/monocyte chemoattractant protein-1 (MCP-1) receptor) and CCR5 (CCL3/MIP-1A receptor) were observed, indicating that these inflammatory signals were activated, but receptors XCR1, CCR4, and ACKR3 were downregulated in the pneumonia group." (PMID 36119044, 2022). "However, the general downregulation of expression of CCL2, CCL3 and CCL5 in the pneumonia cases may be related to decreases in numbers of peripheral T and B lymphocytes." (PMID 36119044, 2022). "We have shown previously that acute infection with the respiratory pathogen, pneumonia virus of mice (PVM), results in local production of the proinflammatory chemokine, CCL3, and that neutrophil recruitment in response to PVM infection is reduced dramatically in CCL3 -/- mice." (PMID 19298652, 2009). "Although the concentrations of IL-13, IL-17A, MIP-1α/CCL3, PAI1, sCD14, IL-1β, CCL11/eotaxin, VEGF/VPF, and RANTES/CCL5 did not exhibit significant differences between the HIV and pneumonia and HIV-only groups, several reasons could explain this lack of disparity." (PMID 38251391, 2024).
depression (23 papers, 2011 to 2025). "CXCL6 and MIP1α/CCL3 add to the growing list of chemokines associated with depression, and a previous meta-analysis supports our finding regarding MIP1α/CCL3 and anhedonia." (PMID 39799156, 2025). "We found that 68.8% of the variance in the phenome of depression was explained by this immune network (positively associated) and CCL3 (inversely associated)." (PMID 38538641, 2024). "At present, it is known that CCL3 may be associated with a delay of the progression of HIV disease; however, whether CCL3 is indeed related to HIV-associated depression warrants further study." (PMID 40313235, 2025). "Similarly, the presence of a CCL3 rs1130371 polymorphism and depression predict increased HAND in PWH." (PMID 36992299, 2023). "CCL3 is a small chemokine belonging to the CC-chemokine family and is one of the most upregulated chemokines during depression." (PMID 38674048, 2024). "The pathogenesis of depression was associated with changes in SPP1, Plasminogen activator inhibitor 1, CCNB1 protein, CCL3, and other genes." (PMID 37932972, 2023). "Using a multivariate linear model, high serum levels of MIP-1β/CCL4 and Eotaxin/CCL11 remained associated with depression (p < 0.01), while, IL-8/CXCL8, MIP-1β/CCL4, MCP-1/CCL2, and MIP-1α/CCL3 were associated with anxiety (p < 0.05) in the symptomatic groups." (PMID 34863117, 2021). "TARC/CCL17 and Eotaxin/CCL11 showed significant associations with high scores for depression (p < 0.04) whereas, MCP-1/CCL2 and MIP-1α/CCL3 were significantly associated with high scores for anxiety (p < 0.05) in the ANX + DEP group." (PMID 34863117, 2021). "Consequently, we can hypothesize that relative decreases in CCL3 secretion may play a role in the depression phenome." (PMID 38538641, 2024). "We observed that the phenome of depression was best predicted by ACE + NLEs, IL-16, TRAIL (all positively), and sIL-1RA and CCL3 (both inversely)." (PMID 38538641, 2024). "We screened depression-related DEGs in the GEO database and combined them with the TCMSP database in this study and concluded that the occurrence of depression was closely related to changes in SPP1, SERPINE1, CCNB1, CCL3, and other genes." (PMID 37932972, 2023). "Meta-analyses and systematic reviews show that levels of IL-1β, IL-2, IL-4, IL-8, the soluble IL-6 receptor (sIL-6R), IL-5, CCL3, IL-17A, and TGF-β1 are significantly changed in depression." (PMID 36614020, 2022). "Positive correlations were observed between MIP-1α/CCL3, MIP-1β/CCL4, MCP-1/CCL2, MIP-3α/CCL20, RANTES/CCL5, Eotaxin/CCL11, and I-TAC/CXCL11 with high scores for anxiety (HARS) (p < 0.05) and for depression (HDRS) (p < 0.004)." (PMID 34863117, 2021). "This meta-analysis indicates that a number of these chemokines (CCL2, CCL3, CCL4, CCL11, CXCL4, CXCL7 and CXCL8) when measured in the blood discriminate between those with and without depression." (PMID 29133955, 2018).
colon carcinoma (22 papers, 2015 to 2025). "It is clear that CCL3 is involved in the pathophysiology of colon cancer: most studies conclude that the elevated level of CCL3 is associated with the development and maintenance of colon cancer." (PMID 41153795, 2025). "Sasaki and colleagues reported that the incidence of colon tumors is suppressed in CCL3- or CCR5-deficient mice treated with AOM/DSS and coincides with lower accumulation of fibroblasts in dysplastic lesions compared with wild-type mice." (PMID 31195598, 2019). "Based on all these findings, CCL3 could be a direct link between colon cancer and the development of CIPN, potentially serving as a risk factor for the latter." (PMID 41153795, 2025). "The authors compared the CCL3-secreting CT26 (L3TU) cell-induced colon tumor to wild-type tumors (WTTU) during the priming phase of the antitumor response." (PMID 41153795, 2025). "By looking at the proposed pathways in which CCL3 is involved in colon cancer and neuropathic pain, one is found to directly overlap." (PMID 41153795, 2025). "Based on current literature data, it is obvious that CCL3 has an important role both in the development of colon cancer and neuropathy." (PMID 41153795, 2025). "This suggests that CCL3 can sustain HB-EGF expression in fibroblasts that are accumulated in the colon tumor." (PMID 41153795, 2025). "The experimental results reveal the mechanism of CCL3 and TNF receptor-associated factor 6 (TRAF6)/NF-κB pathway-related factors and their effects on the proliferation of colon cancer cells." (PMID 35935327, 2022). "Following overexpression of CCL3 in colon cancer HCT116 cells, the expression of Ki67 was increased, and the tumor proliferative ability of cells was enhanced." (PMID 35935327, 2022). "The overexpression of CCL3 in murine colon cancer cells or the subcutaneous injection of CCL3 near the established tumor does not modify the proportion of CD8 T cells but favors their capacity to produce IFNγ." (PMID 36429101, 2022). "In this study, we detected Ki67 in subcutaneous xenograft tumors of colon cancer to further verify that enhanced or weakened secretion of CCL3 is positively correlated with tumor proliferation." (PMID 35935327, 2022). "After CCL3 RNA interference in colon cancer HT29 cells, the expression of Ki67 was decreased, and the tumor proliferative ability of cells was weakened." (PMID 35935327, 2022). "In the current study, we investigate the cellular responses in the tumor-draining lymph nodes (TDLNs) of a CCL3-secreting CT26 colon tumor (L3TU) as compared to wild-type tumor (WTTU) during the priming phase of an antitumor response (≤10 days)." (PMID 29109732, 2017). "This review aims to clarify the role of CCL3 in both colon cancer and CIPN." (PMID 41153795, 2025). "In addition to its role in colon cancer pathophysiology, CCL3 also seems to be involved in neuropathy." (PMID 41153795, 2025). "One may hypothesize that colon cancer contributes to neuropathic pain, at least in part through elevated levels of CCL3, which exerts neurotoxic and pro-nociceptive effects." (PMID 41153795, 2025). "Unfortunately, so far this is the only study that provides evidence for this correlation and there was no study found regarding the association of STAT3 and CCL3 in colon cancer." (PMID 41153795, 2025). "Similar to CCL5, CCL3 has also been linked to increased colon tumor development, although, at least to our knowledge, no relevant impact of this CCR5-binding chemokine on the T cell-mediated control of colon cancer has been described so far." (PMID 36428508, 2022). "In the current study, we examined whether the chemoattractant and cytokine functions of CCL3 in the TDLN could be leveraged to improve immune responses to a murine colon cancer model by engineering tumors to secrete CCL3." (PMID 29109732, 2017).
colon carcinoma (continued). "However, the observed associations were modest, and the investigated correlations (e.g., correlation between circulating levels of CCL3 and the risk of colon cancer development) were not significant after false discovery rate." (PMID 41153795, 2025). "Overexpression of S100A8/S100A9 in mouse colon cancer cells CT26.WT led to differential increases in the secretion levels of various cytokines (CXCL5, CXCL11, GM-CSF, G-CSF, IL1a, IL1b, sTNF RI, and CCL3)." (PMID 38817853, 2024). "The results revealed that CCL3, MMP3, and TIMP1 expression was positively correlated with the infiltration status of immune cells like DCs, CD8+ T cells, and neutrophils in colon cancer." (PMID 36742294, 2023). "Together, these results demonstrate the significance of CCL3, MMP3, and TIMP1 in recruiting and regulating infiltrating immune cells in colon cancer." (PMID 36742294, 2023). "Maraviroc, a CCR5 inhibitor, inhibits murine colon carcinoma cells CT26 and human-derived transplant’s growth and CCL3 expression." (PMID 33981848, 2021). "Another chemokine commonly downregulated was CCL3/MIP-1 alpha, which plays an important role in lymphocyte recruitment, activation, proliferation, and differentiation in colon cancer murine models." (PMID 34611474, 2021). "In the functional study of core down‐regulation factors, it was found that IL6, GM‐CSF, IL11, CCL3 and S100A8/9 increased the viability and decreased the apoptosis rate of colon cancer cells with irradiation and chemical treatment." (PMID 31650683, 2020). "In the functional study of core down‐regulation factors, it was found that IL6, GM‐CSF, IL11, CCL3 and S100A8/9 increased the viability of colon cancer cell lines and decreased the apoptosis rate of colon cancer cells with irradiation and chemical treatment." (PMID 31650683, 2020). "This aim is partially based on a recent study, in which CCL3 was shown to be upregulated in colon tumor bearing mice (with no chemotherapeutic treatment)." (PMID 41153795, 2025). "Hence, we used the TIMER database to analyze the correlation between CCL3, MMP3, and TIMP1 expression and immune cell infiltration status in patients with colon cancer." (PMID 36742294, 2023). "Therefore, we next analyzed if there was a correlation between the expression of hub genes such as CCL3, MMP3, and TIMP1 and infiltrating immune cells in colon cancer." (PMID 36742294, 2023). "In addition, results show a significant positive correlation between CCL3, MMP3, and TIMP1 expression and different immune cell types including dendritic cells, macrophages, CD8+ T cells, and neutrophils in patients with colon cancer." (PMID 36742294, 2023). "In addition, CCL3, MMP3, and TIMP1 expression were negatively correlated with tumor purity in colon cancer (P = 2.30e-8, cor = -0.273; P = 6.68e-5, cor = -0.196 and P = 7.41e-16, cor = -0.385, respectively)." (PMID 36742294, 2023). "Besides, a preliminary study on the interaction between the target factor CCL3 and the differential pathway-related factors (TRAF6, NF-κB, and PI3K) in colon cancer cells was conducted." (PMID 35935327, 2022). "Comparable to these findings, our CT26 colon tumor model does not produce detectable amount of CCL3." (PMID 29109732, 2017).
leukemia (22 papers, 2000 to 2025). A malignant (clonal) hematologic disorder, involving hematopoietic stem cells and characterized by the presence of primitive or atypical myeloid or lymphoid cells in the bone marrow and the blood. "Moreover, deletion of basophil-like leukemia cells recapitulated the phenotypes observed when CCL3-deficient BCR-ABL-transduced HSPCs were injected into the bone marrow of non-irradiated host." (PMID 28829353, 2017). "In leukemia, CCL3 can induce multiple processes that support the dominant proliferation of tumor cells: (i) conversion of normal niche cells to leukemia-adapted cells; (ii) selective inhibition of normal HSPCs; (iii) mobilization of normal HSPCs from BM." (PMID 35371979, 2022). "In this model basophil-derived CCL3 negatively regulates the proliferation of normal hematopoietic stem/progenitor cells and promotes the expansion of leukemia cells." (PMID 33013885, 2020). "This study defines CCL3 as a potential therapeutic target for leukemia progression control in patients with Noonan syndrome." (PMID 32443460, 2020). "In murine models of chronic myelogenous leukemia (CML), CCL3 is critical for the maintenance of a leukemia stem cell population, and leukemia progression." (PMID 30279500, 2018). "CCL3 signaling has been shown to be critical for the maintenance and/or emergence of leukemia initiating cells in CML12,22." (PMID 30279500, 2018). "We have previously identified CCL3 as an abundant leukemia-derived factor in a murine model of blast crisis chronic myelogenous leukemia (bcCML) that also displayed a profound loss of mature osteoblastic cells in the BMME7." (PMID 30279500, 2018). "Detailed analysis on this model identified basophil-like leukemia cells and to a lesser degree, normal basophils as a source of CCL3 in CML bone marrow." (PMID 28829353, 2017). "We further observed that BCR-ABL+lineage−c-kit− immature leukemia cells produced high levels of CCL3, which promoted the development of CML." (PMID 24966464, 2014). "Furthermore, the expression of most M2-associated genes, such as Arg1, CCL3, CCL17, CD206, IL-10, and TGF-β decreases with the infiltration of leukemia cells, whereas the expression of MMP9 and VEGFα increases in the advanced stages of leukemia." (PMID 38779660, 2024). "The cellular populations and several molecular mechanisms involved in leukemic progression also often overlap, with mesenchymal lineage cells and endothelial cells being common targets of leukemia‐derived inflammatory signals (CCL3, TNF, CXCL12) identified across multiple leukemic subtypes." (PMID 34693187, 2021). "Since CCL3 has previously been shown to be critical for the maintenance and emergence of leukemia initiating cells in multiple murine models, it will be important to evaluate any impact of CCL3 inhibition on the normal hematopoietic system as well as the malignancy being treated." (PMID 30279500, 2018). "There is accumulating evidence supporting a crucial involvement of CCL3 in the pathophysiology of several types of leukemia arising from neoplastic transformation of HSPCs, such as chronic myeloid leukemia (CML), acute myeloid leukemia (AML) and chronic lymphocytic leukemia (CLL)." (PMID 28146424, 2017). "In addition to its pro-inflammatory activities, MIP-1α/CCL3 could negatively regulate the proliferation of hematopoietc stem/progenitor cells in leukemia." (PMID 29499727, 2018). "CML red pulp macrophages (RPMs) are able to produce a variety of cytokines and chemokines such as IL-10, CCL3, CCL4, CCL5, CXCL1, TNF-α, and SCF, to sustain leukemia initial cells (LICs)." (PMID 38779660, 2024). "Both Ibrutinib and Acalabrutinib have been shown to decrease levels of CCL3 and CCL4, two critical chemokines inducing migration or homing of leukemia cells, in CLL-cell cultures and their separate clinical trials." (PMID 34174847, 2021).
leukemia (continued). "In a murine model of CML, malignant cells that do not express CCL3 cannot maintain a leukemia stem cell (LSC) population and consequently do not give rise to leukemic disease." (PMID 30279500, 2018). "Moreover, suppression of Treg accumulation in the LHME and delay of leukemia progression could be achieved by blocking the CCL3‐CCR1/CCR5 axis, suggesting there are strong correlation between Treg cells and CCL3." (PMID 41208700, 2025). "The potential roles of the interplay between CCL3 and its receptors may be further supported by the observation that a CCR5 antagonist prevented CML development in nude mice receiving intra-bone marrow injection of BCR-ABL+ leukemia cells, when it was initiated immediately after the injection." (PMID 28829353, 2017).